PCNX1 (pecanex 1)
Synonyms: KIAA0805; KIAA0995; PCNX; PCNXL1; pecanex
Tractability: Antibody: UniProt predicts a signal peptide or a membrane-spanning region. PROTAC: ubiquitination databases record sites on it.
Gene: Protein-coding gene on chromosome 14 (70,907,405 to 71,115,382, forward strand). Ensembl gene ENSG00000100731.
Subcellular location: Membrane
Subcellular location (Human Protein Atlas): Nucleoplasm
Gene Ontology:
Cellular component: membrane
Genetic constraint (gnomAD): Loss-of-function variants: 45 observed, 141.35 expected, observed/expected ratio (o/e) 0.32, 90% interval 0.25 to 0.41. The upper end of that interval is the gene's LOEUF score, 0.41, which puts it in group 1 of 6, group 1 being the genes least tolerant of losing a copy. Missense variants: 1,881 observed, 2,134.5 expected, observed/expected ratio (o/e) 0.88, 90% interval 0.85 to 0.92. Synonymous variants: 748 observed, 789.67 expected, observed/expected ratio (o/e) 0.95, 90% interval 0.89 to 1.01.
Homologues: Orthologues: chimpanzee PCNX1 (99% identical), macaque PCNX1 (99% identical), dog PCNX1 (96% identical), pig PCNX1 (96% identical), rabbit PCNX1 (94% identical), rat Pcnx1 (91% identical), mouse Pcnx1 (91% identical), guinea pig PCNX1 (91% identical), tropical clawed frog pcnx1 (82% identical), zebrafish pcnx1 (67% identical), Drosophila melanogaster pcx (38% identical), Caenorhabditis elegans B0511.12 (31% identical). Paralogues in human: PCNX3 (46% identical), PCNX2 (39% identical), PCNX4 (10% identical).
Diseases named in the same sentence as PCNX1 in open-access papers:
PCNX1 is named in the same sentence as 5 diseases in open-access papers, as found by Europe PMC text mining. Sharing a sentence is not in itself a finding about the gene and the disease. The quoted sentences say what the papers report.
breast carcinoma (1 paper, 2024). "PCNX1, described as hypermutated in glioma, has somatic variants predictive of chemotherapy response in breast cancer." (PMID 38534332, 2024).
PCNX1 also shares sentences with these, for which no sentence is quoted: cancer (1 paper); glioma (1); non-small cell lung carcinoma (1); tumor (1).